SLC17A8 (solute carrier family 17 member 8)
Description:
Multifunctional transporter that transports L-glutamate as well as multiple ions such as chloride, sodium and phosphate. At the synaptic vesicle membrane, mainly functions as an uniporter that mediates the uptake of L-glutamate into synaptic vesicles at presynaptic nerve terminals of excitatory neural cells. The L-glutamate uniporter activity is electrogenic and is driven by the proton electrochemical gradient, mainly by the electrical gradient established by the vacuolar H(+)-ATPase across the synaptic vesicle membrane. In addition, functions as a chloride channel that allows a chloride permeation through the synaptic vesicle membrane that affects the proton electrochemical gradient and promotes synaptic vesicles acidification (By similarity). At the plasma membrane, following exocytosis, functions as a symporter of Na(+) and phosphate from the extracellular space to the cytoplasm allowing synaptic phosphate homeostasis regulation (Probable). The symporter activity is electrogenic. Moreover, operates synergistically with SLC18A3/VACHT under a constant H(+) gradient, thereby allowing striatal vesicular acetylcholine uptake (By similarity).
Synonyms: VGluT3; DFNA25
Tractability: Antibody: UniProt places it where antibodies can reach, with high confidence; UniProt predicts a signal peptide or a membrane-spanning region; its Gene Ontology location is reachable by antibodies, with medium confidence.
Gene: Protein-coding gene on chromosome 12 (100,356,842 to 100,422,055, forward strand). Ensembl gene ENSG00000179520.
Subcellular location: Cytoplasmic vesicle, secretory vesicle, synaptic vesicle membrane; Cell membrane; Synapse, synaptosome
Subcellular location (Human Protein Atlas): Endoplasmic reticulum
Pathways (Reactome):
Disease: Defective SLC17A8 causes autosomal dominant deafness 25 (DFNA25)
Sensory Perception: Sensory processing of sound by inner hair cells of the cochlea
Transport of small molecules: SLC-mediated transport of neurotransmitters
Gene Ontology:
Molecular function: L-glutamate uniporter activity; sodium:phosphate symporter activity; chloride channel activity; L-glutamate transmembrane transporter activity; neurotransmitter transmembrane transporter activity; secondary active transmembrane transporter activity; transmembrane transporter activity
Biological process: L-glutamate transmembrane transport; neurotransmitter loading into synaptic vesicle; phosphate ion homeostasis; L-glutamate import; neurotransmitter transport; positive regulation of glutamate uptake involved in transmission of nerve impulse; regulation of acetylcholine uptake; regulation of synapse structure or activity; sodium-dependent phosphate transport; synaptic transmission, glutamatergic; chloride transmembrane transport; cochlea development; neural retina development; sodium ion transmembrane transport; transmembrane transport
Cellular component: excitatory synapse; synaptic vesicle membrane; apical dendrite; axon terminus; basal dendrite; dendrite; glial limiting end-foot; glutamatergic synapse; multivesicular body; neuronal cell body; pericellular basket; perikaryon; plasma membrane; synapse; synaptic vesicle
Genetic constraint (gnomAD): Loss-of-function variants: 29 observed, 57.19 expected, observed/expected ratio (o/e) 0.51, 90% interval 0.38 to 0.69. The upper end of that interval is the gene's LOEUF score, 0.69, which puts it in group 2 of 6, group 1 being the genes least tolerant of losing a copy. Missense variants: 612 observed, 714.13 expected, observed/expected ratio (o/e) 0.86, 90% interval 0.8 to 0.92. Synonymous variants: 212 observed, 245.28 expected, observed/expected ratio (o/e) 0.86, 90% interval 0.77 to 0.97.
Gene-disease validity (ClinGen):
ClinGen rates the evidence that SLC17A8 causes each of these diseases.
nonsyndromic genetic hearing loss (autosomal dominant): Definitive. A disease characterized by hearing loss that is not part of a larger syndrome.
Homologues: Orthologues: chimpanzee SLC17A8 (99% identical), macaque SLC17A8 (98% identical), dog SLC17A8 (94% identical), mouse Slc17a8 (93% identical), rat Slc17a8 (92% identical), rabbit SLC17A8 (91% identical), pig SLC17A8 (87% identical), tropical clawed frog SLC17A8 (80% identical), zebrafish slc17a8 (78% identical), guinea pig SLC17A8 (73% identical), Drosophila melanogaster VGlut (44% identical), Caenorhabditis elegans eat-4 (43% identical), and 42 more. Paralogues in human: SLC17A6 (72% identical), SLC17A7 (69% identical), SLC17A5 (33% identical), SLC17A4 (28% identical), SLC17A2 (26% identical), SLC17A3 (25% identical), SLC17A1 (24% identical), SLC17A9 (19% identical), SLC37A1 (15% identical), SLC37A4 (15% identical), SLC37A2 (15% identical), SLC37A3 (13% identical).
Diseases named in the same sentence as SLC17A8 in open-access papers:
SLC17A8 is named in the same sentence as 47 diseases in open-access papers, as found by Europe PMC text mining. Sharing a sentence is not in itself a finding about the gene and the disease. The quoted sentences say what the papers report.
deafness (17 papers, 2014 to 2025). An inherited or acquired condition characterized by the complete loss of the ability to hear from one or both ears. "The Slc17a8–/– and Otoferlin–/– mice exhibit profound deafness because both vGlut3 and Otoferlin are heavily involved in the packaging and exocytosis of ribbon synapse vesicles containing the excitatory neurotransmitter glutamate in the IHCs, respectively." (PMID 36687561, 2022). "Of them, 9 deafness genes expressed more in the apical turn (Pou4f3, Slc17a8, Tmc1, Crym, Otof, Ush1c, Pcdh15, Slc26a5, and Lhfpl5) and six were internal controls (Gapdh, Actb, Rps17, Rpl30, Atp6, and Ipo8)." (PMID 24676347, 2014). "Interestingly, of 118 deafness genes, several genes have been reported to be associated with auditory neuropathy, a hearing dysfunction characterized by impaired transmission of signal to the auditory nerve by the presynaptic inner hair cells, such as PJVK, NARS2, SLC17A8, DIAPH3 and DIAPH1." (PMID 37062025, 2023).
Anxiety (13 papers, 2016 to 2025). Intense feelings of nervousness, tension, or panic often arise in response to interpersonal stresses. "Associations between SLC17A8, TRPV1, TRPV4 and TRPM8 gene polymorphisms and anxiety and depression in migraine patients." (PMID 37303955, 2023). "Lastly, SLC17A8 deletion has been shown to induce anxiety related behavior and mild impairments in learning and memory." (PMID 33920826, 2021).
autosomal dominant deafness (8 papers, 2014 to 2024). "Mutations in the SLC17A8 gene coding VGLUT3 cause autosomal dominant deafness linked to auditory synaptopathy." (PMID 36769387, 2023). "In humans, an early report of a 12q22-q24 deletion associated with congenital deafness was later identified as an autosomal dominant nonsyndromic deafness at the DFNA25 locus associated with mutations of SLC17A8." (PMID 32290039, 2020). "The most remarkable finding was a gradient of gene expression changes in four genes (Pou4f3, Slc17a8, Tmc1, and Crym) whose mutations cause autosomal dominant deafness." (PMID 24676347, 2014). "Mutations in the SLC17A8 gene encoding VGLUT3 causes autosomal dominant deafness in humans." (PMID 32098144, 2020). "Especially for genes whose mutations cause autosomal dominant non syndromic hearing loss (Pou4f3, Slc17a8, Tmc1, and Crym) as well as genes important for cochlear function (Emilin-2 and Tectb), gradual expression changes may help to explain the various pathological conditions." (PMID 24676347, 2014). "Patients with a 12q22-q24 deletion in the SLC17A8 gene at the DFNA25 locus have congenital autosomal dominant nonsyndromic deafness." (PMID 39442262, 2024). "Mutation of the SLC17A8 gene is reported to be associated with DFNA25 (deafness, autosomal dominant 25), an autosomal dominant non-syndromic hearing loss (ADNSHL) in humans." (PMID 26797701, 2016). "It is encoded by SLC17A8 in the DFNA25 locus and related to autosomal recessive hearing loss." (PMID 26989561, 2016). "Patients with a 12q22-q24 deletion in the SLC17A8 gene at the DFNA25 locus display congenital and non-syndromic autosomal dominant deafness." (PMID 36769387, 2023).
hearing loss (7 papers, 2011 to 2022). "In human patients, autosomal dominant deafness-25 (DFNA25) is a progressive, high frequency non-syndromic hearing loss caused by a heterozygous mutation in the SLC17A8 gene encoding Vesicular Glutamate Transporter-3 (VGLUT3)." (PMID 30258843, 2018). "The results of gene expression analysis of each cochlear turn showed that 4 ADNSHL genes (Pou4f3, Slc17a8, Tmc1, and Crym) and 9 autosomal recessive non syndromic hearing loss genes (Otof, Strc, Ush1c, Pcdh15, Grxcr1, Dfnb59, Slc26a5, Lhfpl5, and Ptprq) were changed 2-fold or more." (PMID 24676347, 2014). "Other members of the solute carrier family (SLC22A4, SLC26A5, SLC17A8, SLC12A2) have also been associated with non-syndromic hearing loss (hereditaryhearingloss.org)." (PMID 35741759, 2022). "This speculation is consistent with the reported hearing loss types (such as high frequency progressive) in patients with the POU4F3, SLC17A8, TMC1, and CRYM mutations." (PMID 24676347, 2014).
depression (4 papers, 2014 to 2023). "TRPV4 rs3742037, TRPM8 rs17862920 and SLC17A8 rs11110359 were associated with depression in dominant model [ORadj (95% CI): 2.03 (1.06–3.96), p = 0.035; 0.48 (0.23–0.96), p = 0.042; 0.42 (0.20–0.84), p = 0.016, respectively]." (PMID 37303955, 2023). "Interestingly, we found that SLC17A8 rs11110359 polymorphisms were associated with migraine combined depression." (PMID 37303955, 2023). "SLC17A8 rs11110359, TRPV4 rs3742037 and TRPM8 rs17862920 were associated with depression in dominant model (ORadj = 0.42, 95% CI = 0.20–0.84, p = 0.016; ORadj = 2.03, 95% CI = 1.06–3.96, p = 0.035; ORadj = 0.48, 95% CI = 0.23–0.96, p = 0.042, respectively)." (PMID 37303955, 2023).
alcohol use disorder (1 paper, 2024). "In the SUDs patients sample, SLC17A8 mutations were also associated with reduced prevalence of alcohol use disorders (Fisher exact test, p = 0.03)." (PMID 38971801, 2024).
migraine (1 paper, 2023). "Further, we found one novel SHANK1 rs3745521 was associated with migraine with aura risk, and two novel SNPs (rs11110359 and rs11568537 of SLC17A8 gene) were associated with the susceptibility of migraine without aura risk." (PMID 37303955, 2023). "Associations between SLC17A8, SHANK1, TRPV1, TRPV3 and TRPM8 gene polymorphisms and the risk of migraine by aura." (PMID 37303955, 2023).
cancer (1 paper, 2013). A tumor composed of atypical neoplastic, often pleomorphic cells that invade other tissues. "SLC17A8 (also known as Vesicular Glutamate Transporter Type 3, VGLUT3) is a member of the solute carrier (SLC) superfamily encoding multiple transmembrane transporters that may involve in the development and progression of a number of diseases, including cancers." (PMID 23341777, 2013).
tumor (1 paper, 2013). "However, the expression levels of SLC17A8 were very low in lung cancer tumor and adjacent non-tumor tissues." (PMID 23341777, 2013). "However, the mRNA expression level of SLC17A8 could not be detectable (Ct>40) in all of the adjacent non-tumor tissues (n = 46) and most of tumor tissues (n = 43) whereas only 3 subjects were measured with low expression levels in tumor tissues (Ct = 33.7, 36.1 and 39.0)." (PMID 23341777, 2013).
SLC17A8 also shares sentences with these, for which no sentence is quoted: Parkinson disease (5 papers); schizophrenia (4); diabetes (2); eating disorder (2); epilepsy (2); age-related hearing loss (1); Alzheimer disease (1); anxiety disorder (1); atopic dermatitis (1); auditory neuropathy (1); autosomal recessive hearing loss (1); brain disorder (1); brain ischemia (1); cocaine abuse (1); cocaine use disorder (1); cognitive deficits (1); colon cancer (1); drug dependence (1); generalized epilepsy (1); glaucoma (1); Huntington chorea (1); itch (1); kidney diseases (1); mood disorder (1); movement disorder (1); neurological disorders (1); neuropathy (1); non-syndromic deafness (1); ocular albinism (1); Optic neuropathy (1).
A further 8 diseases each share a sentence with SLC17A8 in 1 paper.